ARHGAP42 (Rho GTPase activating protein 42)
Description:
May influence blood pressure by functioning as a GTPase-activating protein for RHOA in vascular smooth muscle.
Synonyms: GRAF3; TMEM133; FLJ32810; AD031
Tractability: PROTAC: ubiquitination databases record sites on it.
Gene: Protein-coding gene on chromosome 11 (100,687,288 to 100,993,941, forward strand). Ensembl gene ENSG00000165895.
Subcellular location (Human Protein Atlas): Nuclear speckles; Cytosol
Pathways (Reactome):
Signal Transduction: CDC42 GTPase cycle; RAC1 GTPase cycle; RAC2 GTPase cycle; RAC3 GTPase cycle; RHOA GTPase cycle
Gene Ontology:
Molecular function: GTPase activator activity
Biological process: activation of GTPase activity; signal transduction
Cellular component: cytoplasm
Genetic constraint (gnomAD): Loss-of-function variants: 42 observed, 81.54 expected, observed/expected ratio (o/e) 0.52, 90% interval 0.4 to 0.67. The upper end of that interval is the gene's LOEUF score, 0.67, which puts it in group 2 of 6, group 1 being the genes least tolerant of losing a copy. Missense variants: 602 observed, 818.94 expected, observed/expected ratio (o/e) 0.74, 90% interval 0.69 to 0.79. Synonymous variants: 284 observed, 291.11 expected, observed/expected ratio (o/e) 0.98, 90% interval 0.88 to 1.08.
Homologues: Orthologues: chimpanzee ARHGAP42 (100% identical), macaque ARHGAP42 (99% identical), rabbit ARHGAP42 (99% identical), pig ARHGAP42 (98% identical), dog ARHGAP42 (97% identical), rat Arhgap42 (97% identical), mouse Arhgap42 (92% identical), guinea pig ARHGAP42 (91% identical), tropical clawed frog arhgap42 (86% identical), zebrafish arhgap42a (73% identical), zebrafish arhgap42b (71% identical), Drosophila melanogaster Graf (40% identical), and 1 more. Paralogues in human: ARHGAP10 (49% identical), ARHGAP26 (49% identical), OPHN1 (48% identical).
Diseases named in the same sentence as ARHGAP42 in open-access papers:
ARHGAP42 is named in the same sentence as 20 diseases in open-access papers, as found by Europe PMC text mining. Sharing a sentence is not in itself a finding about the gene and the disease. The quoted sentences say what the papers report.
diabetes (4 papers, 2020 to 2024). "ARHGAP42 (rs590616, Rho GTPase Activating Protein 42) has been identified as a risk factor for type 2 diabetes mellitus." (PMID 38890579, 2024).
Hypertension (4 papers, 2020 to 2025). The presence of chronic increased pressure in the systemic arterial system. "Although haploinsufficiency of ARHGAP42 has been previously linked to hypertension at adulthood, this is the first time that a homozygous stop-gain variant in ARHGAP42 has been linked to chILD and immune problems." (PMID 34232960, 2021). "We have identified an 8-year-old girl with chILD, systemic hypertension, and immune abnormalities who carries a homozygous stop-gain variant in the ARHGAP42 gene." (PMID 34232960, 2021). "In this study, we identified a patient with chILD, hypertension, and immune abnormalities caused by a rare homozygous stop-gain variant (p.(Glu157Ter)) in exon 5 of ARHGAP42." (PMID 34232960, 2021). "In summary, we have identified a homozygous stop-gain variant in ARHGAP42 in a child with chILD, hypertension, and immune abnormalities." (PMID 34232960, 2021). "This is the first report linking a homozygous stop-gain variant in ARHGAP42 with a chILD disorder, systemic hypertension, and immunological findings in human patient." (PMID 34232960, 2021). "Here, we describe an 8-year-old girl with childhood interstitial lung disease (chILD), systemic hypertension, and immunological findings who carries a homozygous stop-gain variant (c.469G>T, p.(Glu157Ter)) in the ARHGAP42 gene." (PMID 34232960, 2021). "This is the first report to link a homozygous stop-gain variant in ARHGAP42 with a chILD disorder, systemic hypertension, and immunological findings in a pediatric patient." (PMID 34232960, 2021). "ARHGAP42 is involved in regulation of blood pressure and its deficiency causes hypertension in murine models and human adults." (PMID 34232960, 2021). "A recent study also found that haploinsufficiency of ARHGAP42 leads to an age-dependent hypertension in humans." (PMID 34232960, 2021). "Although much effort has been made to understand the mechanism of ARHGAP42 in hypertension, its effect on childhood interstitial lung disease (chILD) and immune abnormalities has not been described." (PMID 34232960, 2021). "The Arhgap42 heterozygous mice also display significant hypertension." (PMID 34232960, 2021). "Arhgap42-deficient mice, homozygous for a gene-trap-mediated reduction in Arhgap42 mRNA levels, exhibit significant hypertension with no other manifestations." (PMID 34232960, 2021). "A hypomorphic Arhgap42-KO mouse model has been described that exhibited significant hypertension but no other overt phenotypes observed for up to 6 months." (PMID 34232960, 2021).
atherosclerosis (2 papers, 2013 to 2022). A disease characterized by the build-up of fatty material and calcium deposition in the arterial wall resulting in partial or complete occlusion of the arterial lumen. "Given the role that both PHACTR1 and ARHGAP42 play in atherosclerosis, osteoporosis and the development of lactation glands in pregnancy, further investigation on the influence of these genes in AM and ANM is warranted." (PMID 23424626, 2013).
nasopharyngeal carcinoma (2 papers, 2018 to 2024). A carcinoma arising from the nasopharyngeal epithelium. "This association is supported by in-vitro data in nasopharyngeal carcinoma cell lines, demonstrating that ARHGAP42 promotes migration capacity and invasiveness of tumor cells." (PMID 38660294, 2024). "In nasopharyngeal carcinoma, elevated expression of ARHGAP42 is associated with reduced metastasis-free survival." (PMID 38660294, 2024). "High expression of ARHGAP42 is associated with poor metastasis‐free survival of nasopharyngeal carcinoma patients." (PMID 29936709, 2018). "Western blot and immunohistochemical staining were used for detecting the expression of ARHGAP42 protein in nasopharyngeal carcinoma tissues and cell lines." (PMID 29936709, 2018). "In the present study, we confirmed that ARHGAP42 was the important marker of nasopharyngeal carcinoma progression and metastasis for the first time." (PMID 29936709, 2018). "Knockdown of ARHGAP42 resulted in significant inhibition of nasopharyngeal cancer cell migration and invasion in vitro, and the overexpression of ARHGAP42 showed the opposite effects." (PMID 29936709, 2018). "ARHGAP42 promotes migration and invasion of nasopharyngeal carcinoma cells in vitro; the antisense lncRNA may be involved in this effect." (PMID 29936709, 2018). "ARHGAP42 is a tumor migration marker and may be a prognostic factor or therapeutic target for patients with nasopharyngeal carcinoma." (PMID 29936709, 2018). "However, the effect of ARHGAP42 in promoting cell malignancy in nasopharyngeal carcinoma is demonstrated in this study." (PMID 29936709, 2018). "In addition, the silence of uc010rul resulted in ARHGAP42 expression decrease and significant inhibition of nasopharyngeal cancer cell migration and invasion." (PMID 29936709, 2018). "Together with previous work, our study highlights ARHGAP42 and uc010rul as novel targets for NPC therapy that may facilitate future nasopharyngeal carcinoma diagnosis and targeted therapy research." (PMID 29936709, 2018).
asthma (1 paper, 2021). "Evaluating the small airways of the Arhgap42-KO mouse model may provide further evidence linking ARHGAP42 with asthma or other chronic airway disease." (PMID 34232960, 2021).
chronic obstructive pulmonary disease (1 paper, 2021). A chronic and progressive lung disorder characterized by the loss of elasticity of the bronchial tree and the air sacs, destruction of the air sacs wall, thickening of the bronchial wall, and mucous accumulation in the bronchial tree. "Recently, a SNP (rs633185) of ARHGAP42 has been reported to be associated with chronic obstructive pulmonary disease, although the relationship between ARHGAP42 and lung diseases has not yet been elucidated." (PMID 34232960, 2021).
immune deficiency (1 paper, 2021). "While immune deficiency associated with defects in ARHGAP42 has not previously been reported, ARHGAP42 and RhoGTPases are important regulators of actin cytoskeletal dynamics." (PMID 34232960, 2021).
lung diseases (1 paper, 2021). "This study is the first to document ARHGAP42 deficiency-associated lung disease and to implicate the RhoA/ROCK pathway as the potential underlying mechanism." (PMID 34232960, 2021).
metastatic carcinoma (1 paper, 2018). A carcinoma which has spread from the original site of growth to another anatomic site. "Microarray and real‐time quantitative PCR were used for a mRNA profiling of ARHGAP42 in nasopharyngeal primary and metastatic carcinoma tissues." (PMID 29936709, 2018).
tumor (5 papers, 2018 to 2024). "Further validation of Arhgap42 and Tcf12, the functions of which in cancer were previously unclear, indicated that both serve as tumor suppressor genes for Brca1-associated tumorigenesis." (PMID 37063417, 2023). "A significant association was detected between ARHGAP21, ARHGAP26, ARHGAP27, ARHGAP 34, ARHGAP 35, ARHGAP42, and ARHGAP46 and the tumor stages." (PMID 38783033, 2024). "Among these genes, six genes are potential regulator of tumor metastasis, including CEMIP, FBN2, TIAM1, ITGA2, ARHGAP42, and GPRIN3." (PMID 38971758, 2024).
cancer (4 papers, 2018 to 2023). A tumor composed of atypical neoplastic, often pleomorphic cells that invade other tissues. "Previous reports have demonstrated that loss of the ARHGAP42 BAR inhibitory domain is associated with decreased RhoA activity and increased cellular motility in vitro, and increased expression of ARHGAP42 in cancer cells is associated with increased cell migration and invasion." (PMID 34232960, 2021). "The ARHGAP42 gene cluster, including the natural antisense lncRNA uc010rul, might serve as a cancer progression marker in patients with NPC." (PMID 29936709, 2018). "However, little is known about the role of ARHGAP42 in cancer development." (PMID 29936709, 2018). "The overexpression and silence experiments of ARHGAP42 were performed in NPC cell lines using siRNA and expressive plasmid for evaluating cancer cell migration and invasion in vitro." (PMID 29936709, 2018). "However, ARHGAP42 showed a very low expression frequency in each cancer tissue (not including NPC)." (PMID 29936709, 2018).
ARHGAP42 also shares sentences with these, for which no sentence is quoted: Alzheimer disease (1 paper); angiosarcoma (1); CHILD syndrome (1); interstitial lung disease (1); Obesity (1); osteoporosis (1); Sepsis (1); Stroke (1); type 2 diabetes mellitus (1).